TGFB1 (transforming growth factor beta 1)
Diseases named in the same sentence as TGFB1 in open-access papers (continued):
Sharing a sentence is not in itself a finding about the gene and the disease.
Myocardial fibrosis (634 papers, 2008 to 2026). "Myocardial fibrosis in these rats is linked to TGFβ activation, and TGFβ1 can induce POSTN expression in cardiac and vascular cells." (PMID 40606601, 2025). "Transforming growth factor beta-1 is considered a key role player in the development of myocardial fibrosis, and in this study, a significant association between serum TGF-β1 and T1 relaxation time was observed in the total cohort." (PMID 40361961, 2025). "Modulation of the TGFβ1/Smad pathway by the SGLT2 inhibitor dapagliflozin has been shown to attenuate myocardial fibrosis and hypertrophy caused by Ang II administration." (PMID 37445888, 2023). "Further, age-associated myocardial fibrosis is decreased in TGFβ1-deficient mice, and ventricular fibrosis is exacerbated in TGFβ1-overexpressing mice." (PMID 38114606, 2023). "Regarding TGFB isoforms, TGFB1 is significantly upregulated after experimental MI and is also a leading cause of myocardial fibrosis and CM hypertrophy." (PMID 35628576, 2022). "The revealed differences suggest a relationshipbetween TGFB1 gene polymorphism and graft myocardial fibrosis." (PMID 35127145, 2021). "This study aims at uncovering any association between the rs1800469, rs1800470,and rs1800471 polymorphisms of the TGFB1 gene and myocardial fibrosis incardiac allograft in heart transplant recipients." (PMID 35127145, 2021). "The findings give grounds forassuming that the TGFB1 gene and its polymorphic variants are involved in theformation of genetic predisposition to myocardial fibrosis in heart transplantrecipients." (PMID 35127145, 2021). "Fibrotic and extracellular remodeling markers Tgfβ1, Mmp2, Timp1, Col1a1, Col3a1, fibronectin and vimentin demonstrated a complex balance underlying myocardial fibrosis at different overload stages." (PMID 31181097, 2019). "In this regard, increased TGFβ1 activity has been implicated in heart and vascular development, hypertension and progressive myocardial fibrosis." (PMID 24465431, 2014). "Moreover, increased collagen volume fraction combined with elevated TGFβ1 implied progressive myocardial fibrosis in Lmna-deficient mouse hearts." (PMID 36082133, 2022). "The myocardial fibrosis marker gene Col1a1, Col3a1, and Tgfb1 were downregulated, correlated with the reversal of Piezo1." (PMID 40344385, 2025). "We found that tRF-Glu-CTC-013 reduced the expression of Tgfb1, Col1a1, Col3a1 and Fn1, thereby inhibiting myocardial fibrosis." (PMID 40520901, 2025). "The use of p38 MAPK inhibitors reduces MAPK/TGFβ-1 expression in the myocardium of pressure-loaded mouse models, thereby inhibiting myocardial fibrosis and restoring cardiac function." (PMID 40997050, 2025). "Studies have shown that during the process of TGFβ1-induced myocardial fibrosis, the expression of MTA3 protein is significantly down-regulated." (PMID 40615041, 2025). "PPARγ activation alleviates oxidative stress and myocardial fibrosis by inhibiting the NF-κB axis and transforming growth factor-beta 1/suppressor of mothers against decapentaplegic (TGF-β1/Smad) pathways, thereby improving cardiac function." (PMID 40734976, 2025). "Studies have shown that QSYQ improves ischemia/reperfusion-induced myocardial fibrosis by regulating TGFβ1/Smads signaling pathway." (PMID 40606601, 2025). "TGFβ1 plays a critical role in matrix remodeling and in enhancing collagen synthesis, and increased expression of TGFβ1 increases myocardial fibrosis." (PMID 38976680, 2024). "In a mouse model of transverse aortic constriction (TAC)-induced HF, treatment with metformin attenuated myocardial fibrosis by inhibiting the TGFβ1-Smad3 signaling pathway." (PMID 38750502, 2024). "These macrophages enhance cardiac hypertrophy and stimulate myocardial fibrosis by producing transforming growth factor beta 1 (TGF-β1), proliferating fibroblasts, activating Smad2/3 signaling, and promoting myocardial fibrosis." (PMID 39682749, 2024).
Myocardial fibrosis (continued). "Some studies have shown that exercise training reduced myocardial fibrosis by downregulating the expression of TGFβ-1-Smad pathway-related proteins." (PMID 36818353, 2023). "It has been reported that when hypertensive myocardial fibrosis occurs, the TGFβ-1-Smad pathway in the myocardium is active, and TGFβ-1 and Smad2/3 are upregulated." (PMID 36818353, 2023). "Myocardial fibrosis is likely secondary to the expression of the pro-fibrotic trophic and mitotic factors, such as TGFβ1 from the cardiac myocytes, which is also observed in other forms of hereditary cardiomyopathy." (PMID 36818425, 2023). "Although some major determinants of myocardial fibrosis are recognised, inhibition of upstream molecules, such as transforming growth factor beta-1 (TGFβ1) has detrimental pleiotropic effects, limiting their viability as therapeutic targets." (PMID 35759180, 2023). "An in vitro study on mice revealed the contribution of CircRNA_010567 in myocardial fibrosis via sponging miR-141, which regulates the expression of transforming growth factor-beta 1 (TGF-β1)." (PMID 36078046, 2022). "The coordinated decrement incurred by resveratrol of diacylglycerol (DAG)/protein kinase A (PKA) and ROS/ERK/TGFβ1 pathways that leads to a reduction of periostin results in an improvement of myocardial fibrosis induced by diabetes." (PMID 36615832, 2022). "Calhex 231, a CaSR inhibitor, suppresses the ITCH-ubiquitin proteasome and TGFβ1/SMADs pathway, thus inhibiting the proliferation of cardiac fibroblasts, reducing collagen deposition, and decreasing glucose-induced myocardial fibrosis." (PMID 33110392, 2020). "BMP7 was proven to limit myocardial fibrosis via attenuating TGFβ1 signaling also in the rat acute myocardial infarction model (AMI)." (PMID 31547567, 2019). "CircRNA_010567 promotes myocardial fibrosis by functioning as a miR-141 sponge, which targets transforming growth factor beta 1 (TGF-β1)." (PMID 30836719, 2019). "ET-1 can also lead to myocardial fibrosis by stimulating transforming growth factor-beta 1 (TGF-β1), which plays a vital role in the occurrence and development of cardiac diseases such as cardiomyopathy, heart valve disease, and arrhythmias." (PMID 31766450, 2019). "Mainly, exogenous administration of recombinant BMP7 decreased TGFβ1 signaling in different areas of the left ventricle, as well as the myocardial fibrosis level and infarct size." (PMID 31547567, 2019). "Studies have shown that TGFβ1-mediated endothelial-to-mesenchymal transition (EndoMT) also contributes to myocardial fibrosis." (PMID 28509980, 2015). "GXD down-regulates the expression of NF-κB target cytokines such as TNF-α, monocyte chemotactic protein-1 (MCP-1), and inhibits the TGFβ1/Smads signaling pathway, thereby inhibiting myocardial type I and type II collagen synthesis and attenuating the cardiac injury cuase by myocardial fibrosis." (PMID 40881586, 2025). "In a recent 2025 study, serum transforming growth factor-beta 1 (TGF-β1) levels correlated with CMR-detected myocardial fibrosis in patients with AS, suggesting potential for integrating blood biomarkers with advanced imaging to quantify ventricular remodeling." (PMID 41346367, 2025). "Furthermore, H2S has been shown to reduce myocardial fibrosis and collagen deposition within atherosclerotic plaques by inhibiting the Transforming Growth Factor Beta 1 (TGF-β1) signaling pathway, thereby delaying the process of vascular remodeling." (PMID 40979186, 2025). "In addition, SGLT2i modulate TGFβ1/Smad signaling in a glycemic-independent manner and attenuate angiotensin II-induced myocardial fibrosis and collagen synthesis." (PMID 40565074, 2025). "Furthermore, they showed that miR-218-5p mediated myocardial fibrosis by inhibition of transforming growth factor beta 1 (TGF-β1)." (PMID 39126028, 2024).
Myocardial fibrosis (continued). "Interestingly, there is convincing evidence demonstrating that KLF15 negatively regulates the expressions of CTGF and TGFB1, two key mediators of myocardial fibrosis, and can ameliorate or even reverse cardiac fibrosis and improve heart function." (PMID 33809104, 2021). "Recently, a study suggested that BMP7 may counteract myocardial fibrosis through limiting the TGFβ1/SMAD3 dependent down-regulation of E-cadherin and up-regulation of collagen I and αSMA in myocardial fibroblasts." (PMID 31547567, 2019). "Interestingly, the cytokine transforming growth factor beta (TGFβ) has been described to influence each of the single components of the remodeling process, i.e., TGFβ1 promotes myocardial fibrosis, cardiomyocyte apoptosis or cardiac hypertrophy." (PMID 25788886, 2015). "Consistently, TGFβ1 overexpression in transgenic mice leads to myocardial fibrosis." (PMID 26068068, 2015). "Genistein can attenuate myocardial fibrosis in T1DMrats, where the underlying mechanisms may be associated to a reduction of serumcreatine kinase MB isozyme (CK-MB), lactate dehydrogenase (LDH) leakage, andsuppression of the TGFβ1/Smad3 signaling pathway." (PMID 39076497, 2024). "Additionally, it inhibits TGFβ1/Smad2 signaling and alleviates myocardial fibrosis in rats." (PMID 33335559, 2020). "For instance, Transforming Growth Factor Beta 1 (TGF-β1): Known for its role in fibrosis, TGF-β1 has been shown to be upregulated in HCM, contributing to myocardial fibrosis and hypertrophy." (PMID 41450821, 2025). "In summary, QSYQ inhibits NLRP3 inflammatory vesicles and inflammatory signaling pathways such as TGFβ1/Smads, STAT3, and NF-κB, and has multi-target anti-myocardial fibrosis properties." (PMID 40881586, 2025). "In summary, the inflammatory factor IL-6 promotes the development of myocardial fibrosis by activating inflammatory signaling pathways such as MAPK and STAT3 and activating TGFβ-1 growth factor." (PMID 40881586, 2025). "BFRT inhibited the TGFβ-1-Smad pathway in the myocardium, downregulated the expression of CTGF, and regulated the balance between MMPs and TIMPs, thereby reducing myocardial fibrosis in SHR, and improving cardiac morphology and function." (PMID 36818353, 2023). "TGFB1 (aging DEG in EC), which is involved in the formation of myocardial fibrosis and promotes cardiac hypertrophy, as upregulated gene in the aged LV." (PMID 37084237, 2023). "One study indicated that four weeks of resistance exercise (8 sets/day, five times/week for 4 weeks) suppresses myocardial fibrosis following myocardial infarction via the upregulation of irisin expression, the activation of AMPK-Sirt1, and the inactivation of TGFβ1-Smad2/3." (PMID 39796197, 2025). "Myocardial fibrosis, assessed by determining CVF, expression levels of a dozen genes involved in fibrosis, and activation of the TGFβ1, was extensive, comprising about 25% of the myocardium, a finding that is in accord with the pro-fibrotic cardiomyopathy caused by the DSP mutations in humans." (PMID 36818425, 2023). "Thus, we considered that RIV attenuated myocardial fibrosis due to, at least partially downregulation of PAR2 and TGFβ1 signaling pathway." (PMID 37786576, 2023). "AGTR1-Agtr1-induced myocardial fibrosis is either directly mediated by the angiotensin II stimulation of AGTR1-Agtr1 or indirectly by the AGTR1-Agtr1-mediated induction of transforming growth factor beta 1, TGFB1-Tgfb1." (PMID 35203304, 2022). "Particularly, resveratrol results in improving adriamycin-induced myocardial fibrosis by increasing SIRT1 and by decreasing factor β1 (TGFβ1), which lead to an increase of glutathione (GSH) and SOD and a decrease of MDA, Hyp, TNF-α and creatine kinase-MB (CK-MB)." (PMID 36615832, 2022). "We speculate that LMW-FGF-2 is both safe and effective when administered in patients at the time of post-MI remodeling when TGFβ1 levels are increased, myofibroblasts are activated, and ECM homeostasis is disturbed toward myocardial fibrosis." (PMID 25948488, 2015).
Myocardial fibrosis (continued). "QSYQ inhibited the TGFβ1/Smads signaling pathway and NLRP3 inflammatory vesicle expression, and significantly suppressed monocyte infiltration and macrophage polarization toward M2, thereby inhibiting MMP-2 and MMP-9 expression and ameliorating I/R induced myocardial fibrosis." (PMID 40881586, 2025). "As a key transcriptional regulator of the TGF‐β pathway, lactylated Snail1 enhances Tgfb1/Smad2 signaling transduction, upregulates TGF‐β expression, and promotes endothelial‐to‐mesenchymal transition (EndoMT), ultimately exacerbating myocardial fibrosis and cardiac dysfunction." (PMID 40599233, 2025). "This lack of colocalization lends support to the notion that EAT's role in the pathogenesis of myocardial fibrosis is mainly through paracrine and endocrine modulators, especially TGFβ1, and therefore direct spatial overlap may not be required." (PMID 36386377, 2022). "The involvement of p38 MAPK in the TGFβ pathway promoted XT-I mRNA and the activity increase were observed in cultured human cardiac fibroblasts stimulated with TGFβ1 and corresponds with an elevated amount of digested GAG content in cardiac tissues from patients with myocardial fibrosis." (PMID 32295230, 2020). "Interstitial and myocardial fibrosis has been reported in HIV-infected patients, and while we did not directly test for the presence of myocardial fibrosis, gene levels of the pro-fibrotic cytokine TGFβ1 were significantly upregulated in the hearts of transgenic rats." (PMID 18439274, 2008).
gastric cancer (617 papers, 1994 to 2026). A primary or metastatic malignant neoplasm involving the stomach. "Both the highly metastatic gastric cancer dataset and the Helicobacter pylori infection dataset exhibit similar trends in TGFβ1 and M2c macrophages, indicating a close association between TGFβ1 and M2c in gastric adenocarcinoma." (PMID 39991579, 2025). "With integrated bioinformatics analysis, BGN, LOX, MMP-9, SERPINE1, and TGFB1 proteins have been selected as suitable diagnostic biomarkers for noninvasive to invasive stages of gastric cancer." (PMID 34054953, 2021). "Results achieved would contribute to establishing TGFB1 gene SNPs as new possible diagnostic and prognostic biomarkers as well as clarifying the actual role of this cytokine in gastric cancer." (PMID 33274798, 2021). "Research on the relationship between the TGFB1 gene polymorphisms and the development of gastric cancer focused mainly on disease susceptibility in case‐control studies, comparing these SNP frequencies between a cohort of patients and a control group." (PMID 33274798, 2021). "In association with TGFB1 in gastric cancer, there are limited studies on this gene's biomarker role." (PMID 34054953, 2021). "In conclusion, analysis of TGFB1 SNPs identified individuals at risk of developing gastric cancer, presenting with a more aggressive form of disease (stage IV) and reduced life expectancy." (PMID 33274798, 2021). "For example, in high-risk Chinese populations, TGFB1 -509C>T was associated with a reduced risk of gastric cancer and the -509T variant genotypes were found to be associated with a decreased risk of among stage I+II cases." (PMID 19835575, 2009). "Previously published data in other types of tumours focused on comparing healthy controls with patients to use these polymorphisms as a diagnostic tool, but few works, especially in gastric cancer, examine TGFB1 as a prognosis tool within the stages of the disease." (PMID 33274798, 2021). "Most studies are about the mutations, variants, and polymorphisms of TGFB1 with gastric cancer." (PMID 34054953, 2021). "Indeed, in gastric cancer cells, hsa-miR-106b and hsa-miR-25 were found to be upregulated and correlated with the loss of tumor suppressor activity of TGFβ-1 signaling." (PMID 31344049, 2019). "Therefore, in this study, by performing bioinformatics analysis, we showed that TGFB1 could also be considered as a diagnostic biomarker for gastric cancer." (PMID 34054953, 2021). "However, the significant association between TGFB1+915 CG/CC genotypes and 2-year survival for all gastric cancer patients suggests that this TGFB1variant may have attenuated the role of TGF-β1 as a tumor suppressor in the earlier stage of tumor progression." (PMID 19566948, 2009). "Therefore, larger studies are warranted to further test whether the TGFB1 variants are associated with gastric cancer risk." (PMID 19835575, 2009). "The GEO dataset results of gastric cancer at different stages showed that some M2 macrophage markers showed consistent changes with TGFβ1." (PMID 39991579, 2025). "TGFβ1 promotes the production of M2c macrophages, which enhance the function and ferroptosis resistance of gastric cancer cells." (PMID 39991579, 2025). "The WB results showed that compared with the blank group, the M2c co culture group had high expression of TGFβ1 protein in gastric cancer cells (Hgc27 and MKN45)." (PMID 39991579, 2025). "In gastric cancer, TGFβ2 correlated with poorer prognosis than TGFβ1, and in malignant gliomas and nasopharyngeal carcinoma, TGFβ2 was associated with malignancy." (PMID 39992949, 2025). "Cell scratch test, migration test, invasion test showed that after co culturing M2c macrophages induced by TGFβ1, the functions of two types of gastric cancer cells (Hgc27 and MKN45) were enhanced to varying degrees." (PMID 39991579, 2025).